MCL1 (MCL1 apoptosis regulator, BCL2 family member)
Diseases named in the same sentence as MCL1 in open-access papers (continued):
Sharing a sentence is not in itself a finding about the gene and the disease.
oral cancer (continued). "The analysis revealed a correlation between the expression of p-EGFR and Mcl-1 proteins in oral cancer cell lines, with the highest coexpression observed in the OSCC cell lines HSC-3, SAS, and Ca9.22." (PMID 38888847, 2025). "Next, we investigated mTOR and its related proteins to determine the link between EGFR and Mcl-1 signaling by afatinib in oral cancer cell lines." (PMID 38888847, 2025). "Mcl-1 is known to be regulated by EGFR signaling pathway in cancer, but there is a lack of research into the clinical correlation between EGFR and Mcl-1 in cancer, particularly, oral cancer." (PMID 38888847, 2025). "Previous studies have shown that afatinib can target the EGFR/mTOR/Mcl-1 axis, inducing tumor cell apoptosis, and has the potential to become a treatment strategy for oral cancer." (PMID 40696350, 2025). "Mcl-1 protein overexpression has been demonstrated in diverse cancers ranging from solid tumors including oral cancers as reported by our group to hematological malignancies." (PMID 36045907, 2022). "Sanguisorba officinalis and C. officinale Makino, C. bursapastoris, and Dianthus chinensis and Acalypha australis were found to reduce Mcl-1 via Sp1 and induce apoptosis in oral cancer cell lines." (PMID 35524332, 2022). "Several kinase inhibitors have been shown to downregulate Mcl-1 in oral cancer; e.g., the aurora-A kinase inhibitor, alisertib, degraded Mcl-1 in HPV E7-expressing head and neck SCC cells." (PMID 35524332, 2022). "The combination of thioridazine and carboplatin induced apoptosis by downregulating c-FLIP and Mcl-1, indicating that Mcl-1 can be used as a molecular target of combination therapy in oral cancer." (PMID 35524332, 2022). "LncRNA FGD-AS1 inhibited the proliferation and migration/invasion of oral cancer, acting as a sponge for miR-153-3p and miR-153-3p to inhibit Mcl-1 expression." (PMID 35524332, 2022). "Based on our present review, Mcl-1 appears to be an effective anticancer target that can be used in the therapeutic management of oral cancers." (PMID 35524332, 2022). "Many natural compounds are known to affect STAT3, which is known as one of the major upstream molecules of Mcl-1 in oral cancers." (PMID 35524332, 2022). "Mcl-1 overexpression is well documented in various solid and hematological tumors, including oral cancer, and has been demonstrated as genetic amplifications and in mRNA and protein levels." (PMID 35524332, 2022). "The activity of Mcl-1 in oral cancer is found to be regulated by paracrine signaling mechanisms, physical forces, or intracellular regulatory mechanisms." (PMID 35524332, 2022). "Mithramycin A reduced the expression of Mcl-1 in oral cancer cells, leading to an increase in Bax protein, followed by its translocation into the mitochondria and oligomerization." (PMID 35524332, 2022). "Mcl-1 is frequently amplified and upregulated in cancerous lesions of oral cavity and affects the clinical progression and survival of patients with oral cancer." (PMID 35524332, 2022). "Benzyl isothiocyanate led to a reduction in Mcl-1 followed by the development of mitochondria-mediated apoptosis in oral cancer." (PMID 35524332, 2022). "This review also successfully summarized the agents, both synthetic and natural, that have an inhibitory effect on Mcl-1 in oral cancer." (PMID 35524332, 2022). "Berberine modulates apoptosis in oral cancer cells by inhibiting the expression of cycloxygenase-2 and Mcl-1." (PMID 36144625, 2022). "In oral cancers, our laboratory has reported primarily increased levels of Mcl-1 transcripts which correlated well with the overall increase in the Mcl-1 protein levels." (PMID 36045907, 2022). "In particular, our previous findings have shown that Mcl-1 inhibition induced by naturally occurring compounds in oral cancer cells is involved in lysosome- or proteasome-dependent degradation." (PMID 34391437, 2021).
oral cancer (continued). "Bufalin has been shown to inactivate Na+/K+-ATPase in bladder carcinoma cells, reduce the expression of human telomerase reverse transcriptase in colorectal, pancreatic, and oral cancer cells, and down-regulate Mcl-1 expression in NSCLC cells." (PMID 32219334, 2020). "TW-37 enhanced the cytotoxicity of human oral cancer cell lines by inducing caspase-dependent apoptosis, which correlates with the reduction of the myeloid cell leukemia-1 (Mcl-1) expression via transcriptional and post-translational regulation." (PMID 32863764, 2020). "The ectopic expression of Mcl-1 partially attenuated the apoptosis-inducing capacity of TW-37 in human oral cancer cell lines." (PMID 32863764, 2020). "Our analysis of the effect of TW-37 on anti-apoptotic Bcl-2 family proteins in human oral cancer cell lines revealed that TW-37 suppressed the Mcl-1 expression at the transcriptional and post-translational levels, resulting in apoptosis." (PMID 32863764, 2020). "The results showed that these STAT3 inhibitors significantly decreased the cell viability and induced apoptosis in human oral cancer cell lines via the downregulation of Mcl-1." (PMID 32863764, 2020). "Further studies indicated the AKT/myeloid cell leukemia 1 (Mcl-1) signaling pathway is responsible for the observed cytotoxicty of evodiamine in oral cancer cells." (PMID 30380774, 2018). "Since MCL-1 is overexpressed in oral cancer cells and serve as an important prosurvival protein, we probed into its critical involvement in the maintenance of mitochondrial homeostasis in OSCC cells." (PMID 28947954, 2017). "Aberrant expression of antiapoptotic BCL-2 family proteins, particularly MCL-1 has been reported in diverse human cancers including oral cancers." (PMID 28947954, 2017). "In oral cancer cells, metformin treatment was found to partly induce apoptosis through miR-26a-induced downregulation of Mcl-1." (PMID 28881582, 2017). "We have previously reported overexpression of anti-apoptotic members of the BCL-2 family, particularly MCL-1 (Myeloid Cell Leukemia-1) over their pro-apoptotic counterparts in human oral cancers." (PMID 28947954, 2017). "Radiation followed by chemotherapy is the common treatment modality for oral cancer and Mcl-1 overexpression has been shown to provide resistance to conventional chemotherapeutic drugs like Cisplatin." (PMID 25409302, 2014). "The present study aimed to evaluate the clinicopathological significance of the expression of three known Mcl-1 isoforms in oral tumors and the effect of targeting Mcl-1L isoform on chemosensitivity of oral cancer cells." (PMID 25409302, 2014). "The effect of Mcl-1L shRNA or Obatoclax (a small molecule Mcl-1 inhibitor), in combination with Cisplatin on chemosensitivity of oral cancer cells was also assessed." (PMID 25409302, 2014). "The present study was thus undertaken to evaluate the clinical significance of Mcl-1 isoforms in oral cancer and the efficacy of targeting Mcl-1 to chemosensitize oral cancer cells in vitro." (PMID 25409302, 2014). "So far, limited information is available on the role of Mcl-1 isoforms in pathogenesis of oral cancer." (PMID 25409302, 2014). "The Mcl-1 mRNA levels were correlated with clinicopathological parameters and outcome of oral cancer patients." (PMID 25409302, 2014). "Recent studies from our laboratory have demonstrated significant overexpression of Mcl-1 protein in oral cancer cell lines, premalignant lesions (OSF) and oral tumors by immunohistochemistry." (PMID 25409302, 2014). "Further, we have also demonstrated Mcl-1 to be a prognostic factor in oral cancer patients treated with definitive radiotherapy." (PMID 22873792, 2012). "At our laboratory Mcl-1, an anti-apoptotic member of the Bcl-2 family has been demonstrated to be overexpressed in oral cancers and to predict outcome in oral cancer patients treated with definitive radiotherapy." (PMID 22873792, 2012).
oral cancer (continued). "Our findings suggest that targeting the EGFR/mTOR/Mcl-1 axis with afatinib could be a promising therapeutic strategy for oral cancer treatment, particularly in patients with high EGFR and Mcl-1 co-expression." (PMID 38888847, 2025). "Afatinib treatment induced apoptosis and suppressed Mcl-1 in oral cancer cell lines without the EGFR T790M mutation." (PMID 38888847, 2025). "Taken together, these results indicate that EGFR and Mcl-1 are correlated and coexpressed in oral cancer, suggesting that both factors may contribute to poor prognosis among oral cancer patients." (PMID 38888847, 2025). "There was a strong correlation between EGFR and Mcl-1 expressions in oral cancer patients." (PMID 38888847, 2025). "Therefore, the key factors that inhibit Mcl-1 can be used as potential treatment strategies in the treatment of oral cancer." (PMID 35524332, 2022). "Mithramycin inhibits Mcl-1 and RNAi regulates Bax to induce apoptosis in oral cancer cell lines." (PMID 35524332, 2022). "FBW7 stabilizes Mcl-1 and promotes Mcl-1 addiction in oral cancer." (PMID 35524332, 2022). "Isolated reports on the regulation and interactions of Mcl-1 in oral cancer have been identified." (PMID 35524332, 2022). "Moreover, pharmacological inhibition of USP9X potently induced cell death in oral cancer cells through rapid degradation of Mcl-1." (PMID 36045907, 2022). "Thus, further study to investigate the involvement of the magnolol-induced downregulation of Mcl-1 in oral cancer is required." (PMID 34680412, 2021). "This study reported that the ectopic expression of Mcl-1 partly declined the apoptotic activity of TW-37 in human oral cancer cell lines, suggesting that regulation of the Mcl-1 expression is needed for TW-37-induced apoptosis in human oral cancer cell lines." (PMID 32863764, 2020). "As TW-37 is a potent inhibitor of anti-apoptotic Bcl-2 family proteins, such as Bcl-2, Bcl-xL, and Mcl-1, we assessed whether TW-37-induced apoptosis in human oral cancer cell lines could regulate these proteins." (PMID 32863764, 2020). "In addition, we confirmed that αldiginoside inhibited the proliferation of oral cancer cells by inhibiting Mcl-1." (PMID 33114727, 2020). "We have earlier demonstrated that the prosurvival MCL-1 protein contributes to therapy resistance and poor prognosis in oral cancers and thus may prove to be a potential therapeutic target in OSCC." (PMID 28947954, 2017). "In this study, Bcl-2, Bcl-xL and Mcl-1 expression levels decreased in DA-treated oral cancer cells." (PMID 26356821, 2015). "Fourth, DA inhibits Bcl-2, Bcl-xL and Mcl-1 expression in oral cancer cells." (PMID 26356821, 2015). "Our recent studies indicate Mcl-1 to be important for the survival of oral cancer cells and hence targeting Mcl-1 could be useful in treatment of oral cancer patients." (PMID 25409302, 2014). "We have previously reported the overexpression of Mcl-1 protein in human oral cancers." (PMID 25409302, 2014). "Correlation of Mcl-1 isoform expression & clinicopathological parameters in oral cancer patients." (PMID 25409302, 2014). "In the present study, we assessed the expression of Mcl-1 isoforms (Mcl-1L, Mcl-1S & Mcl-1ES) in oral tumors versus normal tissues, to determine whether they would be useful as prognostic markers in oral cancer patients." (PMID 25409302, 2014). "MCL-1 is one of the antiapoptotic members of the BCL-2 family, and it has been verified that MCL-1 expression level was significantly upregulated in OSCC tumor tissues and is linked to poor outcome, therapeutic resistance, and disease progression of oral cancers 34-37." (PMID 38706892, 2024). "Although the development of direct Mcl-1 inhibitors remains challenging, this review will help researchers and clinicians to identify the avenues that can be investigated to provide better disease prediction and therapeutic planning of oral cancers expressing Mcl-1 in the future." (PMID 35524332, 2022).
oral cancer (continued). "Thus, we next investigated whether TW-37 treatment for 24 or 48 h could regulate the protein stability of Mcl-1 in human oral cancer cell lines." (PMID 32863764, 2020). "Based on the related literature, this study hypothesizes that the transcriptional regulation of Mcl-1 in human oral cancer cell lines upon TW-37 treatment could correlate with the signal transducer and activator of transcription (STAT) family members, including STAT3 (H1)." (PMID 32863764, 2020). "Hence, seeking a Mcl-1-targeting inhibitor could provide a potential therapeutic benefit for oral cancer therapy." (PMID 32863764, 2020). "Thus, our findings indicate that the decreased expression of Mcl-1 protein induced by TW-37 in human oral cancer cell lines could arise from the inhibition of STAT3 activation and nuclear translocation, thereby validating H1 of this study." (PMID 32863764, 2020). "Selective inhibitors like Obatoclax, which specifically overcome Mcl-1 mediated resistance, is already in phase 2 clinical trials and may have important therapeutic implications, when used in combination with radiotherapy in treatment of oral cancer patients." (PMID 22873792, 2012). "Afatinib, targeting the EGFR/mTOR/Mcl-1 axis, shows promise as a therapeutic strategy for oral cancer, especially in patients with high EGFR and Mcl-1 expressions." (PMID 38888847, 2025). "This study investigates the role and effectiveness of the epidermal growth factor receptor (EGFR) tyrosine kinase inhibitor (TKI) in oral cancer, focusing on the clinical relevance of EGFR and myeloid cell leukemia-1 (Mcl-1) in head and neck cancers (HNCs)." (PMID 38888847, 2025). "In human oral cancer OC2 cells in vitro, BITC inhibits growth and triggers apoptosis by reducing Mcl-1 and Bcl-2 expression and increased PARP cleavage." (PMID 30970087, 2019). "Although small molecule inhibitors that directly target Mcl-1 by interrupting the PPIs have been developed, no drugs that can directly target this protein have been used in the treatment of oral cancer to date." (PMID 35524332, 2022). "Despite evidence on the role of Mcl-1 as an important molecular target in oral cancer, the molecular mechanisms involved in oral cancer have not been well documented compared with those in other cancers." (PMID 35524332, 2022). "Mcl-1 is tightly regulated at the transcriptional, post transcriptional and translational levels and the exact mechanism of Mcl-1 overexpression in oral cancers is not known." (PMID 25409302, 2014). "Our studies with obatoclax (GX15-070), one of the pan-Bcl-2 inhibitors capable of inhibiting Mcl-1, demonstrated a potent single-agent activity against oral cancer cells in vitro and in vivo by inducing a rather non-canonical form of cell death, namely “necroptosis”." (PMID 36045907, 2022). "Moreover, in our present study, shRNA mediated down regulation of Mcl-1L has shown to chemosensitize oral cancer cells (AW8507, UPCI:SCC040 & UPCI:SCC029B) to Cisplatin indicating a crucial role for Mcl-1 in treatment resistance in oral cancers." (PMID 25409302, 2014). "Mcl-1 has also been shown to play a role in chemoresistance of a variety of cancers, but the role of its isoforms in chemoresistance has not been studied in cancers including oral cancers." (PMID 25409302, 2014). "Also, there is no information available on the expression of Mcl-1 isoforms in oral cancers." (PMID 25409302, 2014).
liver cancer (27 papers, 2011 to 2025). An epithelial or non-epithelial malignant neoplasm that arises from the liver. "According to relevant literature reports, imperatorin has the ability to cause Mcl-1 degradation, which then releases Bak and Bax and activates the intrinsic apoptosis pathway, causing multidrug-resistant liver cancer cells to undergo apoptosis." (PMID 36110518, 2022). "In conclusion, metformin induces apoptosis of liver cancer cells and decreases the translation activity of the mRNA encoding for the anti-apoptotic protein Mcl-1." (PMID 28881582, 2017). "In this study, we report that metformin induces apoptosis of liver cancer cells and inhibits translation of the mRNA encoding the anti-apoptotic protein Mcl-1." (PMID 28881582, 2017). "PPP1R15A positively regulated MCL-1 expression in liver cancer cells, which is an essential survival factor in many cancers." (PMID 39948597, 2025). "In human liver cancer, imperatorin acted as a chemosensitizer via downregulating Mcl-1 expression and cooperatively triggering Bax translocation and Bak activation." (PMID 38914663, 2024). "Studies have shown that Mcl-1, an important anti-apoptotic protein in the mitochondrial apoptotic pathway, is overexpressed in liver cancer cells and liver cancer stem cells." (PMID 36386146, 2022). "Inhibited the proliferation of liver cancer cells by blocking the cell cycle transition, and downregulated the expression of Mcl-1 to promote cell apoptosis." (PMID 35011278, 2021). "Others indicated that bile salt-induced Mcl-1 phosphorylation enhanced Mcl-1 stability by blocking HUWE1-mediated degradation in human liver cancer (HepG2) cells." (PMID 34065298, 2021). "Fibulin-1 silencing significantly increased apoptosis in liver cancer cell lines upon nutrient starvation by downregulating Mcl-1 and Bcl-xL expression." (PMID 32612994, 2020). "MCL1 was found to be overexpressed in liver cancer and knockdown of MCL1 sensitizes liver cancer cells to chemotherapy drugs." (PMID 31467488, 2019). "We found that these effects are mediated by 4E-BPs, as if these translational repressors are silenced, liver cancer cells are resistant to the apoptotic effect of metformin, and translation of Mcl-1 mRNA is sustained." (PMID 28881582, 2017). "Simultaneously, 3-formylchromone inhibits the expression of Bcl-2, Bcl-xL, Survivin, and Mcl-1 in liver cancer cells, suggesting that 3-formylchromone promotes apoptosis in liver cancer cells by suppressing the STAT3 pathway and weakening CXCL12-driven metastasis." (PMID 38920657, 2024). "Notably, TRAF6‐dependent phosphorylation of ERK1/2 induces upregulation of MCL‐1, ultimately suppressing apoptosis in liver cancer cells." (PMID 37484971, 2023). "Interestingly, MCL-1 sequestration by A-1210477 was sufficient to induce BCL-xL-dependent cell death in liver cancer cell lines, such as HepG2 and Hep3B." (PMID 32024199, 2020). "Moreover, although deletion of BAK significantly inhibited hepatocyte apoptosis in Mcl-1 knockout mice, deletion resulted in reduced incidences of liver cancer, reduced TNFα production, oxidative stress and oxidative DNA damage in non-cancerous livers." (PMID 30404157, 2018). "Thus, Mcl-1 and Bcl-xL are the predominant mediators of Fibulin-1 siRNA-induced apoptosis in liver cancer cells, although other unidentified targets may also be involved." (PMID 32612994, 2020). "MCL-1 degradation induced by ROS/JNK signaling activation has been reported in the lung and liver cancer." (PMID 37352173, 2023). "Accordingly, liver cancer cells with reduced 4E-BP1/2 expression are more resistant to metformin-induced apoptosis, alongside sustained translation of Mcl-1 mRNA and protein expression." (PMID 28881582, 2017).